PTGS2 (prostaglandin-endoperoxide synthase 2)
Diseases named in the same sentence as PTGS2 in open-access papers (continued):
Sharing a sentence is not in itself a finding about the gene and the disease.
intracerebral hemorrhage (3 papers, 2021 to 2024). A cerebrovascular disorder characterized by bleeding into one or both cerebral hemispheres including the basal ganglia and the cerebral cortex. "Therefore, upregulation of the PTGS2 gene indicates that LXTYF may reduce the risk of blood pressure elevation, which is conducive to antihypertensive therapy in the early stage of an intracerebral hemorrhage." (PMID 33727915, 2021).
myeloma (3 papers, 2022 to 2024). "As for myeloma, NF-κB pathway-related genes, IRF1, COX2/PTGS2, CSF-1, IL-4R, STAT1, STAT3, STAT6, and IL-8 is high expression, promoting MDSC maturation and infiltration, thereby enhancing the TIME." (PMID 38720342, 2024).
pharyngitis (3 papers, 2020 to 2024). Inflammation of the throat most often caused by viral and bacterial infections. "DC, CC, and BC analysis indicated that ALB (serum albumin), PPARγ (peroxisome proliferator-activated receptor gamma), MAPK3 (mitogen-activated protein kinase 3), EGF (epidermal growth factor), and PTGS2 (prostaglandin G/H synthase 2) are closely related to pharyngitis." (PMID 33101439, 2020).
pulpitis (3 papers, 2023 to 2025). Inflammation of the dental pulp. "ROS and Fe2+ levels significantly rose, and immunohistochemistry showed low expression of GPX4 and high expression of PTGS2 in pulpitis." (PMID 41087337, 2025). "P. gingivalis is associated with increased PTGS2 expression, PGE2 secretion, and the development of pulpitis." (PMID 37287452, 2023). "In rat pulpitis models, both prothymosin α (PTMA, precursor of thymosin α1) gelatin sponge placed at the hole of pulp (LPS-P(gs)) and PTMA injection in pulp (LPS-P(i)) significantly reduced infiltration of inflammatory cells and expression of PTGS2, and increased the expression of GPX4." (PMID 41087337, 2025).
Salmonella Infections (3 papers, 2016 to 2025). Infections with bacteria of the genus SALMONELLA. "Interestingly, these sex-dependent differences by Agmo KO were attenuated under Salmonella infection, likely due to the associated dominant upregulation of Ptgs2 in both WT and Agmo KO tissues." (PMID 40474257, 2025).
sarcoidosis (3 papers, 2019 to 2024). Sarcoidosis is a multisystemic disorder of unknown cause characterized by the formation of immune granulomas in involved organs. "Additionally, a promoter variation in prostaglandin-endoperoxide synthase 2 (PTGS2), −765G>C, has been identified as another potential risk factor for fibrotic disease in sarcoidosis." (PMID 38202248, 2023). "Several other non-HLA genes have been associated with sarcoidosis, such as prostaglandin G/H synthase/cyclooxygenase (PTGS2/COX2), neurogenic locus notch homolog 4 (NOTCH4), nucleotide-binding oligomerization domain-containing protein 2 (NOD2), and Butyrophilin-like 2 (BTNL2)." (PMID 31126090, 2019). "In addition, several genetic variants within or near non-HLA genes were also significantly associated with sarcoidosis: BTNL2, PTGS2/COX2, and PACERR (PTGS2 Antisense NFKB1 Complex-Mediated Expression Regulator RNA)." (PMID 31126090, 2019). "For example, our data are consistent with a prior study showing an association between SNP rs20417, in a non-coding region of the PTGS2/COX2 gene on chromosome 1, and sarcoidosis in a UK and Austrian Caucasian cohort without known environmental exposure." (PMID 31126090, 2019).
sarcoma (3 papers, 2015 to 2024). A usually aggressive malignant neoplasm of the soft tissue or bone. "Specifically, in sarcoma, the expression level of SMC4 is significantly correlated with monocyte markers CD14 and CSF1R, TAM marker CD80, and M1 macrophage marker PTGS2." (PMID 36719264, 2023).
steatosis (3 papers, 2017 to 2025). Increased lipid within the cytoplasm of cells. "We found that the elevated iron concentrations in serum and liver tissues, increased PTGS2 and ALOX12 expression, and higher hepatic MDA levels were observed in Insig2 KO mice following steatosis I/R injury compared to WT mice." (PMID 40169542, 2025).
synovial sarcoma (3 papers, 2014 to 2025). "The six unshared genes (CEBPB, BMP6, PTGS2, DMP1, FGF2, and H2AFV) are likely the important contributors to the ossifying phenotype seen in the metastatic synovial sarcomas." (PMID 32290096, 2020).
tendinopathy (3 papers, 2017 to 2019). "This increase in both SPM and eicosanoids in tendon derived stromal cells from patients with tendinopathy was coupled with a significant increase in the expression of several of their biosynthetic enzymes including ALOX12, ALOX15 and PTGS2." (PMID 28887458, 2017).
thrombosis (3 papers, 2018 to 2025). "In the current study, COL5A1, VCAN, PTGS2, ITGAV and ITGA8 were five hub genes revealed to be closed associated with thrombosis-prone plaques." (PMID 41415585, 2025). "Therefore, we believed that Aspirin may participate in the treatment of atherosclerotic plaque rupture with thrombosis by targeting the PTGS2 gene." (PMID 41415585, 2025). "Among them, COL5A1, VCAN, PTGS2, and ITGAV showed extremely significant increases (P < 0.01); ITGA8 was significantly decreased in the plaque group and thrombosis group (P < 0.01)." (PMID 41415585, 2025).
thyroid tumor (3 papers, 2019 to 2023). A benign or malignant neoplasm affecting the thyroid gland. "Another round goes like, M2-like polarized macrophages turned from human monocytes showed an upregulation of PTGS2, and the coexpression of M2 markers and PTGS2 was found in a specific part of human thyroid tumors." (PMID 35432535, 2022). "This highlights the link between PTGS2-expressing thyroid tumor cells and M2-macrophages, further corroborated by tissues displaying low expression of both markers (class co-expression low)." (PMID 31113465, 2019). "The expression of PTGS2 and M2 markers in thyroid tumors was investigated in publicly available datasets." (PMID 31113465, 2019). "Co-expression of PTGS2 and M2 markers is observed a significant fraction of human thyroid tumors." (PMID 31113465, 2019). "PTGS2, HOXA1, TMEFF2, p16, and PTEN genes were hypermethylated in FNAC of thyroid tumor when compared between the tumor and healthy tissue." (PMID 36975440, 2023).
vasculitis (3 papers, 2014 to 2025). "In vasculitis, proteins like PTGS2 are crucial in mediating inflammation via prostaglandin synthesis." (PMID 39954672, 2025).
angiosarcoma (2 papers, 2010 to 2022). A malignant tumor arising from the endothelial cells of the blood vessels. "Additional work will be required to clarify the role of PTGS2/COX-2 in hemangiosarcoma." (PMID 21062482, 2010).
cervical adenocarcinoma (2 papers, 2012 to 2021). An adenocarcinoma arising from the cervical epithelium. "HeLa cervical adenocarcinoma cells were treated with 1∶100 dilution of SP or vehicle (PBS) for 6 hours and the mRNA expression of PTGS1 and PTGS2 was determined by quantitative RT-PCR analysis." (PMID 22442729, 2012). "Using HeLa cervical adenocarcinoma cells, we found that seminal plasma (SP) induced the expression of the inflammatory enzymes, prostaglandin endoperoxide synthase (PTGS1 and PTGS2), cytokines IL-6, IL-11 and the angiogenic factor VEGF-A in vitro." (PMID 22442729, 2012). "Using HeLa cervical adenocarcinoma cells, we found that seminal plasma (SP) induced the expression of the inflammatory enzymes, prostaglandin endoperoxide synthase (PTGS1 and PTGS2), cytokines interleukin (IL) -6, and -11 and vascular endothelial growth factor-A(VEGF-A)." (PMID 22442729, 2012).
cervical intraepithelial neoplasia (2 papers, 2022 to 2024). "We have previously shown a gradual increase in the expression of proliferation markers and a decrease in the expression of proapoptotic genes (estrogen receptor ESR1, progesterone receptor PGR, PTEN, and PTGS2) for progressive degrees of cervical intraepithelial neoplasia leading to cancer." (PMID 35736434, 2022).
cholestasis (2 papers, 2017 to 2022). Impairment of the bile flow caused by obstruction within the liver, or outside the liver in the bile duct system. "Moreover, Q7R can also reduce TNF-α, IL-1β, PTGS1, PTGS2, NCOA2, and NF-κB levels and alleviate the inflammatory response caused by cholestasis." (PMID 36699093, 2022).
delirium (2 papers, 2024 to 2025). A disorder characterized by confusion; inattentiveness; disorientation; illusions; hallucinations; agitation; and in some instances autonomic nervous system overactivity. "Prostaglandin endoperoxide synthase-2 expression levels, white blood cell counts, and pain scores mediated the reduction of postoperative delirium incidence by parecoxib." (PMID 39903567, 2025). "Prostaglandin endoperoxide synthase-2 mediates neuroinflammatory processes in postoperative delirium." (PMID 39903567, 2025). "Secondary outcomes were cumulative incidences of emergence delirium and prostaglandin endoperoxide synthase-2 levels, inflammatory cell counts, and pain score on postoperative day 1 and postoperative adverse events." (PMID 39903567, 2025). "The effective anti-inflammatory activity of prostaglandin endoperoxide synthase-2 inhibition by parecoxib and postoperative pain control may be important mechanisms for preventing postoperative delirium." (PMID 39903567, 2025).
diabetic cardiomyopathy (2 papers, 2024 to 2025). Diabetic cardiomyopathy is a disorder of the heart muscle in people with diabetes. "It suppressed NF-κB translocation in streptozocin-induced diabetic cardiomyopathy and inhibited PTGS2 activity in tumor cells." (PMID 39458839, 2024).
endometrial adenocarcinoma (2 papers, 2010 to 2011). "PTGS2 expression is elevated in numerous neoplastic diseases including endometrial adenocarcinomas resulting in elevated biosynthesis of PGE2." (PMID 21589857, 2011). "Moreover, we have shown that elevated PGF2α-FP receptor signalling in endometrial adenocarcinoma leads to upregulation of tumorigenic genes such as PTGS2 and angiogenic genes such as FGF2 and VEGF which regulate vascular function in a paracrine manner." (PMID 20840749, 2010). "Furthermore our data propose a novel molecular mechanism whereby PGE2 biosynthesis, driven by elevated expression of PTGS2 in endometrial adenocarcinoma cells, and hypoxia synergise to increase PTGER4 expression and subsequently enhance cell proliferation and tumour growth." (PMID 21589857, 2011). "One the major targets of Akt signalling in endometrial adenocarcinoma cells, is prostaglandin endoperoxide synthase (PTGS) 2 (also called cyclooxygenase 2)." (PMID 21589857, 2011).
familial Mediterranean fever (2 papers, 2017 to 2025). Familial Mediterranean fever (FMF) is an autoinflammatory disorder characterized by recurrent short episodes of fever and serositis resulting in pain in the abdomen, chest, joints and muscles. "These factors were IL-1β, prostaglandin-endoperoxide synthase 2 (PTGS2/COX-2), NOD-like receptor family CARD domain-containing protein 4 (NLRC4), Familial Mediterranean Fever (MEFV) gene, and caspase 5 (CASP5)." (PMID 40861543, 2025).
gastric tumor (2 papers, 2020 to 2025). "The expression of ACTA2, HIF1A, and VEGFA was independently associated with TJP1 in non-cancerous tissue, explaining 90% in its variability, and BCL2, HIF1A, CDKN1A, and PTGS2 were independently associated with TJP1 in gastric tumors, explaining 98% in gene variability." (PMID 32630408, 2020). "The expression of PTGS2, BCL2, and IL7 (inversely) was independently associated with CCL2 in non-cancerous tissue, explaining 88% in gene variability, and HIF1A and BCL2 were independently associated with CCL2 in gastric tumors, explaining 83% in its variation." (PMID 32630408, 2020). "The expression of PTGS2 was independently associated with ACTA2 in non-cancerous tissue, explaining 38% in gene variability, and BCL2 was independently associated with ACTA2 in gastric tumors, explaining 39% in gene variability." (PMID 32630408, 2020).
gastroenteritis (2 papers, 2021 to 2023). An inflammatory disorder that affects the upper and lower gastrointestinal tract. "The involvement of PTGS2 was crucial in several key aspects of mucosal defense, making a substantial contribution to the resolution of gastroenteritis and playing a significant role in the regulation of ulcer healing." (PMID 37375548, 2023).
gonococcal infection (2 papers, 2024). "In addition to CXCL8 and IL1B, we also observed multiple genes previously shown to be involved in responses to gonococcal infections, including PTGS2 and ICAM1." (PMID 38976720, 2024). "This hypothesis is supported by studies from multiple groups showing that anti-apoptotic factors, including BCL2A1 (Bfl-1), BIRC3 (c-IAP-2), and PTGS2 (Cox-2), are upregulated upon gonococcal infection of epithelial monolayers lacking ciliated cells." (PMID 38704381, 2024).
HIV-1 infection (2 papers, 2011 to 2014). The type species of lentivirus and the etiologic agent of acquired immunodeficiency syndrome (AIDS). "In order to assess the potential of PTGS2 to independently impact HIV-1 infection, we transiently expressed the human PTGS2 protein in human PBMC cells." (PMID 21533265, 2011).
Hyperkalemia (2 papers, 2020 to 2024). An abnormally increased potassium concentration in the blood. "Hyperkalemia also stimulates the expression of PTGS2, which plays an important role in the rat LSCC and has been suggested as a therapeutic target for LSCC." (PMID 33092550, 2020).
hyperplastic polyp (2 papers, 2008 to 2016). A polyp found mainly in the stomach and colon. "Additionally, the expression level and ROC analysis of Aurora-A mRNA and PTGS2 mRNA in adenomatous polyps and hyperplastic polyps showed a comparable result to that of miR-137." (PMID 27764771, 2016).
hypopharyngeal carcinoma (2 papers, 2012 to 2023). Carcinoma, predominantly squamous cell, arising from the epithelial cells of the hypopharynx. "However, only four genes have been reported to inhibit the chemosensitivity in HSCC or hypopharyngeal carcinoma, including PTGS2, PHF20, ABCC1, and MCL1." (PMID 37791141, 2023).
hypothyroidism (2 papers, 2021 to 2025). Abnormally low levels of thyroid hormone. "In our study, we showed that the PTGS2 protein level was significantly lower in the group of rats with induced hypothyroidism in comparison to the control group of animals." (PMID 34573602, 2021). "The mRNA level of PTGS2 was significantly higher in the group with hypothyroidism than the control group, while the protein level of PTGS2 was significantly lower in the group with hypothyroidism." (PMID 34573602, 2021).
infiltrating ductal carcinoma (2 papers, 2014 to 2024). "In the current study, we used an immunohistological approach to compare expression of α3 integrin (ITGA3) and COX2 (PTGS2) among clinical samples of human invasive ductal carcinoma (IDC), and to determine whether there is a correlative relationship between them." (PMID 24950714, 2014).
intervertebral disc degeneration (2 papers, 2023 to 2025). "PTGS2 expression is elevated during intervertebral disc cell senescence, and its inhibition has been reported to alleviate aging and slow intervertebral disc degeneration." (PMID 41323819, 2025).
kidney cancer (2 papers, 2023 to 2024). Primary or metastatic malignant neoplasm involving the kidney. "Our previous in silico protein–protein interaction (PPI) and molecular docking studies revealed that the isoquercitrin compound could trigger potential cancer-causing gene targets, such as IGF1R, PIK3CA, IL6, and PTGS2, which can regulate kidney cancer and inflammation." (PMID 38666938, 2024). "In our previous study, we also found that PTGS2, PIK3CA, IGF1R, and IL6 commonly caused kidney cancer and inflammation, and by suppressing these genes, we can reduce the severity of kidney cancer and inflammation." (PMID 38666938, 2024). "Our previous study predicted using protein-protein interaction (PPI) and molecular docking analysis that the isoquercitrin compound can control kidney cancer and inflammation by triggering potential gene targets of IGF1R, PIK3CA, IL6, and PTGS2." (PMID 38666938, 2024). "In summary, IQ can trigger the gene targets of PTGS2, IGF1R, and PIK3CA, which in turn regulate kidney cancer and inflammation." (PMID 38666938, 2024). "So, all results validated the finding that isoquercitrin treatment can suppress PTGS2, PIK3CA, and IGF1R expression and thus control kidney cancer and inflammation." (PMID 38666938, 2024). "Furthermore, we performed in vitro validation of IQ efficacy using RT-PCR and qRT-PCR assays and confirmed that IQ can trigger PTGS2, PIK3CA, and IGF1R gene targets to control kidney cancer and inflammation." (PMID 38666938, 2024). "Thus, we can conclude that isoquercitrin inhibits the expression of PTGS2, PIK3CA, and IGF1R gene targets, which in turn controls kidney cancer and inflammation." (PMID 38666938, 2024).
laryngeal squamous cell carcinoma (2 papers, 2020 to 2021). A squamous cell carcinoma that arises from the larynx.
mucositis (2 papers, 2022 to 2023). Mucositis is inflammation and damage of the mucous membranes lining the mouth and other parts of the gastrointestinal (GI) tract. "Its anti-mucositis effect may be through regulating TNF/NF-κB pathway and inhibiting inflammatory mediators PTGS2 and NOS2." (PMID 36278232, 2022).
nephritis (2 papers, 2023). Inflammation of renal tissue. "After identifying the main targets (TNF, AKT1 and PTGS2) of SHP in nephritis treatment, we further conducted a KEGG analysis to reveal the signal pathways of these main targets." (PMID 37361210, 2023). "The results showed that TNF, AKT1 and PTGS2 were the main targets of SHP in treating nephritis, which was consistent with previous reports." (PMID 37361210, 2023). "Our results demonstrated that TNF, AKT1 and PTGS2 might be the key targets of SHP in the treatment of nephritis." (PMID 37361210, 2023). "The protein interaction analysis network showed that TNF, VEGFA, PTGS2, MMP9, MAPK1, and other proteins were the key targets of the 7 phenolic acids in the treatment of nephritis." (PMID 36998608, 2023). "Thus, the regulation of TNF, AKT1 and PTGS2 may contribute to the treatment of nephritis." (PMID 37361210, 2023). "The key targets such as TNF, VEGFA, PTGS2, MMP9, and MAPK1 are directly or indirectly related to the 7 phenolic acids and multiple nephritis-related pathways." (PMID 36998608, 2023).
neuritis (2 papers, 2022 to 2023). A neuropathy arising from inflammation of one or more nerves. "The mRNA expressions of PLA2G4A and PTGS2 in neuritis causing multiple cerebral infarctions increased significantly as compared to those in normal subjects." (PMID 37741847, 2023).
non-alcoholic steatohepatitis (2 papers, 2025). "PTGS2 (degree = 14) amplifies inflammatory cascades by converting FASN-derived arachidonic acid into protumorigenic prostaglandin E2, establishing a self-perpetuating lipid-inflammation feedforward loop that drives IL-6/STAT3-mediated malignant transformation in non-alcoholic steatohepatitis." (PMID 40839202, 2025).